THBD (thrombomodulin)
Description:
Endothelial cell receptor that plays a critical role in regulating several physiological processes including hemostasis, coagulation, fibrinolysis, inflammation, and angiogenesis. Acts as a cofactor for thrombin activation of protein C/PROC on the surface of vascular endothelial cells leading to initiation of the activated protein C anticoagulant pathway. Also accelerates the activation of the plasma carboxypeptidase B2/CPB2, which catalyzes removal of C-terminal basic amino acids from its substrates including kinins or anaphylatoxins leading to fibrinolysis inhibition. Plays critical protective roles in changing the cleavage specificity of protease-activated receptor 1/PAR1, inhibiting endothelial cell permeability and inflammation (By similarity). Suppresses inflammation distinctly from its anticoagulant cofactor activity by sequestering HMGB1 thereby preventing it from engaging cellular receptors such as RAGE and contributing to the inflammatory response.
Synonyms: TM; CD141; THRM; BDCA-3; AHUS6; BDCA3; THPH12
Tractability: Small molecule: a structure with a bound ligand is known. Antibody: its Gene Ontology location is reachable by antibodies, with high confidence; UniProt predicts a signal peptide or a membrane-spanning region. PROTAC: ubiquitination databases record sites on it.
Safety:
Unwanted effects reported when the protein is acted on. In parentheses: how it was acted on, where the effect was seen, and who reports it.
Hemorrhage (source: ClinPGx)
Gene: Protein-coding gene on chromosome 20 (23,045,633 to 23,049,672, reverse strand). Ensembl gene ENSG00000178726.
Subcellular location: Membrane
Subcellular location (Human Protein Atlas): Cytosol; Nucleoplasm
Pathways (Reactome):
Hemostasis: Cell surface interactions at the vascular wall; Regulation of clotting cascade
Gene Ontology:
Molecular function: protein binding; signaling receptor activity; calcium ion binding; transmembrane signaling receptor activity
Biological process: negative regulation of blood coagulation; blood coagulation; blood coagulation, common pathway; negative regulation of fibrinolysis; negative regulation of platelet activation; proteolysis; zymogen activation; negative regulation of coagulation
Cellular component: cell surface; plasma membrane; serine-type endopeptidase complex; external side of plasma membrane; membrane
Genetic constraint (gnomAD): Loss-of-function variants: 2 observed, 1.04 expected, observed/expected ratio (o/e) 1.92, 90% interval 0.51 to 1.94. That is too few expected variants to judge how well the gene tolerates losing a copy. Missense variants: 850 observed, 729.54 expected, observed/expected ratio (o/e) 1.17, 90% interval 1.1 to 1.23. Synonymous variants: 449 observed, 336.76 expected, observed/expected ratio (o/e) 1.33, 90% interval 1.23 to 1.44.
Gene-disease validity (ClinGen):
ClinGen rates the evidence that THBD causes each of these diseases.
thrombomodulin-related bleeding disorder (autosomal dominant): Moderate.
thrombomodulin-related bleeding disorder (autosomal recessive): Limited.
atypical hemolytic-uremic syndrome (autosomal dominant): Disputed. A rare, genetic thrombotic microangiopathy due to dysregulation of the alternative complement pathway and characterized by the triad of hemolytic anemia, thrombocytopenia, and acute renal dysfunction.
Homologues: Orthologues: chimpanzee THBD (98% identical), macaque THBD (88% identical), dog THBD (74% identical), pig THBD (70% identical), mouse Thbd (68% identical), rat Thbd (66% identical), guinea pig THBD (59% identical), Drosophila melanogaster knk (15% identical), Drosophila melanogaster CG34355 (15% identical), Caenorhabditis elegans W01C8.5 (9% identical).
Diseases named in the same sentence as THBD in open-access papers:
THBD is named in the same sentence as 259 diseases in open-access papers, as found by Europe PMC text mining. Sharing a sentence is not in itself a finding about the gene and the disease. The quoted sentences say what the papers report.
Sepsis (147 papers, 2005 to 2026). Sepsis is defined as life-threatening organ dysfunction caused by a dysregulated host response to infection. "The SCARLET trial examined the effect of recombinant human soluble thrombomodulin in patients presenting with sepsis-associated coagulopathy." (PMID 39759543, 2025). "Anticoagulants such as recombinant human soluble thrombomodulin (rhTM) and antithrombin are used to treat sepsis-associated DIC; however, their efficacy remains controversial." (PMID 40740948, 2025). "Another example of predictive enrichment is the randomized trial of thrombomodulin versus placebo, in which patients were selected for inclusion based on the presence of sepsis-associated coagulopathy." (PMID 41157190, 2025). "Regarding anticoagulant therapies, recombinant human thrombomodulin (rhTM), an anticoagulant targeting excessive thrombin generation, has been widely used in Japan for sepsis-associated DIC." (PMID 40692784, 2025). "A randomized controlled trial showed that recombinant thrombomodulin (rhTM) had an increasing trend in survival in sepsis with suspected sepsis-associated DIC." (PMID 38167115, 2024). "Of note, sepsis induces the loss of some crucial anticoagulants, such as protein C, antithrombin (AT), and thrombomodulin (TM)." (PMID 38167115, 2024). "In the meta-analyses, improved survival was reported using antithrombin and thrombomodulin for sepsis-associated DIC." (PMID 39302568, 2024). "In Japanese sepsis guidelines, recombinant thrombomodulin is recommended for sepsis-associated disseminated intravascular coagulation." (PMID 38658435, 2024). "The mainstream management strategies in septic coagulopathy include the causal treatment of sepsis, unfractionated heparin, low-molecular-weight heparin, antithrombin, and recombinant human thrombomodulin." (PMID 36673595, 2023). "In particular, recombinant thrombomodulin was suggested to be administered to patients with sepsis-associated disseminated intravascular coagulation (DIC) in a recent report." (PMID 36366167, 2022). "We investigated the age-related differences in the survival benefit of anticoagulant therapy, defined as the administration of antithrombin, recombinant human thrombomodulin, and their combination in sepsis in accordance with the JAAM DIC diagnostic criteria." (PMID 35660774, 2022). "The decrease in thrombomodulin expression in the endothelium results in a hypercoagulable state and sepsis-associated disseminated intravascular coagulation (DIC)." (PMID 35130927, 2022). "Sepsis phenotypes were similar in the validation cohort, and thrombomodulin treatment was also associated with lower 28-day (RD: − 24.9% [95% CI − 49.1 to − 0.7%]) and in-hospital mortality (RD: − 30.9% [95% CI − 55.3 to − 6.6%])." (PMID 33741010, 2021). "We examined the latent phenotypes of sepsis with coagulopathy and the associations between thrombomodulin treatment and the 28-day and in-hospital mortality for each phenotype." (PMID 33741010, 2021). "The present study indicated that a coagulopathy-associated THBD promoter SNP, rs2239562, had a significant influence on the outcome as well as the progress of severe sepsis/septic shock." (PMID 35083232, 2021). "Further, a recent study demonstrated that one of the THBD SNPs, rs1962, was related to the risk of death in the patients with sepsis." (PMID 35083232, 2021). "Higher mortality on severe sepsis in the discovery and combined cohorts was significantly associated with the CC genotype in a THBD promoter SNP (−1920*C/G; rs2239562) [odds ratio [OR] 2.709 (1.067–6.877), P = 0.033 and OR 1.768 (1.060–2.949), P = 0.028]." (PMID 35083232, 2021). "Accordingly, we postulated that some of the THBD single nucleotide polymorphisms (SNPs) are associated with susceptibility to and/or mortality of sepsis." (PMID 35083232, 2021).
Sepsis (continued). "Although the polymorphisms of protein C genes, for example, PROC(−1641), are already demonstrated to be associated with the mortality and organ failures of sepsis, there is only limited investigation of the thrombomodulin gene THBD." (PMID 35083232, 2021). "The phase 3 multinational SCARLET study evaluated the efficacy and safety of a recombinant human soluble thrombomodulin (ART-123) for treatment of sepsis-associated coagulopathy (SAC), which correlates with increased mortality risk in patients with sepsis." (PMID 33788052, 2021). "Among anticoagulants, recombinant thrombomodulin (rTM) is a potential therapeutic agent for sepsis-associated DIC14." (PMID 33060764, 2020). "Studies showed potential benefits of recombinant human-soluble thrombomodulin (rhTM) and antithrombin for treating sepsis associated disseminated intravascular coagulation." (PMID 31956416, 2020). "Recombinant thrombomodulin (rTM) has been used for treatment of sepsis-associated disseminated intravascular coagulation." (PMID 33060764, 2020). "Despite an increase of THBD in serum is associated with poorer outcome in sepsis, its circulating form as well as that of SDC1 reduces IL-6 expression, thereby serving to control an inflammatory response and preventing overwhelming immune reactions." (PMID 31396019, 2019). "Based on these reports, we think that the results of the current study suggested the additive effects of recombinant thrombomodulin to antithrombin therapy in patients with sepsis-associated DIC." (PMID 29098447, 2017). "Despite this, some studies have reported that anticoagulation with drugs such as heparin, antithrombin, and recombinant human soluble thrombomodulin (rhTM) may be effective in sepsis-associated DIC, although these results remain controversial." (PMID 40740948, 2025). "Similar findings have been reported for recombinant thrombomodulin in sepsis-associated DIC." (PMID 39430208, 2024). "Consequently, recombinant thrombomodulin is recommended for sepsis-associated DIC in Japanese sepsis guidelines." (PMID 37221630, 2023). "Due to the exclusive nature of the non-NSTI control group, it was not possible to retrieve similar samples for validation, and instead the sepsis cohort was also used as a comparative cohort to test the predictive value of the NST-associated biomarker thrombomodulin." (PMID 34263738, 2021). "A decrease in expression of VEGF was observed, whereas there was an increase in the expression of angiopoietin-2, tissue plasminogen activator, thrombomodulin, and von Willebrand factor, leading to an increase in thrombus and associated with the increase in mortality in sepsis." (PMID 35052592, 2021). "Elevated serum thrombomodulin level is associated with sepsis severity and risk of death." (PMID 34722755, 2021). "Our data indicate a high level of Syndecan-1 is associated with increased mortality, and is associated with increased levels of thrombomodulin, pro-inflammatory cytokines, hsCRP, and procalcitonin, which suggests the presence of serious endothelial damage, inflammation, and sepsis in these patients." (PMID 34861818, 2021). "In addition, the present study aimed to evaluate the role of thrombomodulin in the pathophysiology of sepsis through a genetic association study with Japanese multicenter cohorts, focusing on the THBD gene polymorphisms." (PMID 35083232, 2021). "Seven biomarkers indicating endothelial dysfunction (mid‐regional proadrenomedullin (MR‐ProADM), syndecan 1, thrombomodulin, angiopoietin 2, endothelial cell‐specific molecule 1, vascular cell adhesion molecule 1 and E‐selectin) had stronger associations with sepsis than infection alone." (PMID 32073224, 2020). "Specifically, increased TNF in sepsis may be associated with increased EC F3 expression and TF production, as well as down-regulation of THBD and PROCR, resulting in decreased APC generation for suppression of FVIII and FV inactivation." (PMID 32029851, 2020).
Sepsis (continued). "As previously reported, the serum thrombomodulin is elevated in diseases associated with endothelial injury, such as acute respiratory distress syndrome, disseminated intravascular coagulation, and organ dysfunction induced by sepsis." (PMID 28771554, 2017). "In addition, increased serum thrombomodulin levels on days 1 and 3 after the diagnosis of sepsis were also associated with an increased risk of mortality." (PMID 28771554, 2017). "Besides, increased serum thrombomodulin levels have also been reported in conditions other than sepsis that cause ischemic and/or inflammatory endothelial injuries." (PMID 28771554, 2017). "The systemic inflammatory response induced by sepsis leads to activation and depletion of coagulation factors and platelets, impaired fibrinolytic function, disruption of the vascular endothelial barrier, and loss of physiologic antithrombotic factors such as thrombomodulin." (PMID 37875995, 2023). "Therefore, the present data indicating that a THBD polymorphism influenced the susceptibility, as well as the outcome of sepsis, might be key in the pathogenesis of aHUS." (PMID 35083232, 2021). "Recombinant human soluble thrombomodulin (rhsTM) is a therapeutic agent for sepsis-induced disseminated intravascular coagulation (DIC) and is reported to be associated with bleeding events." (PMID 40230734, 2025). "In sepsis, inflammatory cytokines inhibit the expression of thrombomodulin, an anticoagulant in the vascular endothelium, and increase coagulation activation." (PMID 40230734, 2025). "Since protein C is activated by the binding of thrombin and TM, reduced thrombomodulin leads to procoagulant changes in sepsis." (PMID 38225597, 2024). "While some guidelines recommend only supportive therapies, the Japanese sepsis guidelines recommend early detection and early initiation of anticoagulation by antithrombin (AT) or recombinant human soluble thrombomodulin (rTM)." (PMID 38225597, 2024). "Studies applied machine learning to identify patients displaying certain sepsis phenotypes and responding to recombinant human thrombomodulin (rhTM) therapy." (PMID 38921759, 2024). "High plasma thrombomodulin levels are correlated with increased mortality in patients with sepsis and DIC." (PMID 36836706, 2023). "The value of recombinant thrombomodulin in sepsis-induced coagulopathy was recently evaluated in a multinational, randomized controlled phase III trial (including patients with a platelet count < 50 × 109/L and a prothrombin time ratio > 1.4)." (PMID 36836706, 2023). "Murine data corroborated these results with lower Angpt-1 and higher soluble thrombomodulin among knockout mice with sepsis relative to the wildtype." (PMID 36778250, 2023). "Elevation of soluble plasma thrombomodulin with a concomitant decrease in endothelial surface thrombomodulin is observed in sepsis-induced DIC." (PMID 36836706, 2023). "A similar result was described in a reanalysis of sepsis patients treated with recombinant thrombomodulin, which was shown to only benefit patients with a severe coagulopathy phenotype." (PMID 38020105, 2023). "Serum thrombomodulin levels can be used as an early predictor of mortality and disease severity in pediatric sepsis patients." (PMID 36793336, 2023). "Other biomarkers, such as serum thrombomodulin have been established for adult sepsis but recently demonstrated a prognostic value for pediatric sepsis." (PMID 36793336, 2023). "This study aimed to evaluate the application of presepsin (P-SEP) and thrombomodulin (TM), which are biomarkers of sepsis and endothelial dysfunction, respectively, in the prognosis of COVID-19." (PMID 38057335, 2023). "For pediatric sepsis, the most established biomarkers include C-reactive protein, erythrocyte sedimentation rate, procalcitonin, ferritin, serum thrombomodulin, CD64, and Il-8." (PMID 36793336, 2023).
Sepsis (continued). "Another top gene identified in this study was ELAVL1, which encodes HuR protein, playing a critical role in post-transcriptional regulation, splicing and suppression of thrombomodulin synthesis in interleukin-1β (IL-1β) treatment and sepsis." (PMID 35938548, 2022). "Physiologic anticoagulation systems, including the AT–heparan sulfate system and thrombomodulin–protein C system, prevent unfavorable thrombosis; however, these systems are readily impaired during sepsis." (PMID 36293332, 2022). "Recombinant human thrombomodulin (rhTM) has been suggested as an adjunct therapy for patients with sepsis." (PMID 35590381, 2022). "In sepsis, the expression of endothelial anticoagulant proteins, including thrombomodulin, is suppressed by endothelial damage." (PMID 35130927, 2022). "It is known that extracellular histones are procoagulant and involved in the coagulopathy of sepsis via endothelial damage, platelet activation, thrombin generation, and affecting regulatory pathways, such as protein C, thrombomodulin, and fibrinolysis." (PMID 36552012, 2022). "Recombinant human thrombomodulin (rhTM) has anti-inflammatory and anticoagulation activities, and it has been suggested as an adjunct therapy for patients with sepsis, particularly those with sepsis-induced coagulopathy." (PMID 33741010, 2021). "Thrombomodulin, an integral endothelial cell membrane protein, is cleaved and released into the bloodstream during sepsis and septic shock, leading to elevated levels of serum thrombomodulin in pediatric and adult sepsis patients." (PMID 34722755, 2021). "Here, we aimed to show that thrombomodulin (TM)-mediated suppression of NET formation protects against organ damage in sepsis." (PMID 34066510, 2021). "Circulating endothelial MPs carrying endothelial protein C receptor and thrombomodulin have been detected in circulating blood of severe sepsis patients and were further elevated with the progression of sepsis-induced disseminated intravascular coagulation." (PMID 34769139, 2021). "Recombinant human thrombomodulin has anticoagulation effects and was shown to be beneficial for patients with sepsis and coagulopathy in observational studies and in a subgroup analysis of a phase II trial." (PMID 33741010, 2021). "The suggested biomarker for necrosis, thrombomodulin, showed a high discriminatory power for NSTIs even when compared with the heterogeneous sepsis patient group." (PMID 34263738, 2021). "Currently, soluble recombinant human thrombomodulin (rhTM) is undergoing clinical evaluation for the treatment of severe sepsis." (PMID 32344575, 2020). "At the moment, there is little clinical evidence to support the use of thrombomodulin to treat sepsis." (PMID 33679715, 2020). "Activated protein C, which is converted from protein C via a complex of thrombin and thrombomodulin, promotes fibrinolysis and suppresses thrombus and inflammation during inflammatory activation in sepsis." (PMID 33679715, 2020). "Thrombomodulin acts as dual regulator in coagulation and inflammation, making it a promising target for immunothrombosis in sepsis." (PMID 33679715, 2020). "Previous studies demonstrated that thrombomodulin is excessively secreted into bloodstream in severe illnesses such as sepsis and ARDS." (PMID 32122329, 2020). "This is due to the fact that in sepsis, after thrombomodulin has been down-regulated by inflammatory cytokines, the conversion of protein C to activated protein C is suppressed." (PMID 33679715, 2020). "In the comparison of sepsis and septic shock, the number of biomarkers of endothelial dysfunction independently associated with septic shock dropped to four (SDC1, MR‐ProADM, THBD and ANGPT2)." (PMID 32073224, 2020). "Favorable effects of thrombomodulin administration have been reported not only in sepsis-induced coagulopathy but also in disseminated intravascular coagulations with various backgrounds." (PMID 31416465, 2019).